BRCA1 (BRCA1 DNA repair associated)
Diseases named in the same sentence as BRCA1 in open-access papers (continued):
Sharing a sentence is not in itself a finding about the gene and the disease.
tumor (continued). "In the second sample, a BRCA1 frameshift mutation (c.2806_2809delAAAC p.(Ala938fs)) was not recognized by tumor sequencing because of poor coverage and sequence quality at the mutation site." (PMID 34202525, 2021). "Therefore, BRCA1 and BRCA2-deficient tumor cells are very dependent on PARP for repair, and for this reason, PARPi has a significant effect on DNA damage in such tumor cells, showing great cytotoxicity." (PMID 35095931, 2021). "A total of 603 samples, from 600 patients, were received for BRCA1/2 tumor testing at UHN within the study period, including 518 surgical resections (2 from distant sites), 81 biopsies, 2 cytology samples, and 2 with unknown origin." (PMID 33030818, 2021). "Further supporting this observation, mouse models of BRCA1 mutant breast and ovarian cancer show that PARPi treatment, in addition to mediating cytotoxicity via synthetic lethality, triggers T cell-dependent anti-tumor immunity." (PMID 34572943, 2021). "The BRCA1 is involved in tumor suppression and homologous recombination repair in response to DNA breaks and may be a modulator of mitotic spindle assembly." (PMID 33880365, 2021). "However, over the last years, tumor resistance mechanisms towards PARP inhibitor treatment were reported, such as reversion mutations in BRCA1 and BRCA2, loss of BRCA1 promoter hypermethylation, or overexpression of RAD51." (PMID 34356606, 2021). "Consequently, BRCA1/2 tumor testing is now recommended at the time of initial diagnosis of HGSC for the purposes of determining PARPi treatment eligibility." (PMID 33030818, 2021). "The identified variants encode proteins lacking the domains required for BRCA1 interaction and tumour suppressor functions." (PMID 33672422, 2021). "So, we wondered whether any of the DEGs between Brca1 mutant luminal and tumor cells could serve as driver and/or marker for the tumorigenesis." (PMID 34815798, 2021). "As BRCA1 or RAD51C gene silencing through promoter methylation has been detected in ovarian and breast tumours and has been associated with HRD cases, a potential mechanism of resistance to PARPi in these tumours would involve gene re-expression." (PMID 35008208, 2021). "Silencing of BRCA1 in SUM149 revertant cells also caused SIRT inhibitior synthetic lethality, suggesting a causal relationship between BRCA1 status and SIRT inhibitor synthetic lethality, as it did in non-tumour breast epithelial MCF10A cells." (PMID 34750509, 2021). "Although most BRCA1/2 carriers developed later-onset esophagogastric cancer, 28.6% of patients had early-onset disease, including a 35-year-old BRCA2 carrier whose tumor also carried a second somatic BRCA2 variant, suggesting that the germline BRCA2 variant contributed to carcinogenesis." (PMID 34251444, 2021). "CircPLEKHM3 was found to function as a tumor suppressor in OC by sponging miR-9 to regulate the endogenous expression of breast cancer 1 (BRCA1), DNA heat shock protein family (Hsp40) member B6 (DNAJB6) and kruppel like factor 4 (KLF4) which consequently inactivates oncogenic AKT1 signaling." (PMID 33614648, 2021). "Consistent with the findings derived from tumor tissues, primary p18mt;Brca1+/- and p18mt;Gata3+/- tumor cells also exhibited a typical mesenchymal-like morphology with a high level of EMT markers, whereas, epithelial-like morphology were observed in p18mt and MMTV-PYMT tumor cells." (PMID 34373738, 2021).
tumor (continued). "As MDA-MB-436 cells could be established as tumour xenografts in rats, we assessed the ability of a Polθ inhibitor to target established BRCA1/SHLD2 defective tumours in vivo." (PMID 34140467, 2021). "The presence of BRCA1/2 mutations or tumour genomic instability (HRD score ≥ 42) is surrogate markers of HR deficiency, and a positive immune score is a surrogate of interferon-primed immune checkpoints in the tumour microenvironment." (PMID 34465315, 2021). "However, the roles of BRCA1/2 alteration in tumor immunotherapy remains uncharacterized, to our knowledge." (PMID 33961040, 2021). "Thus, we tested the efficacy of concurrent treatment with AZD2281 and irradiation radiotherapy in controlling tumor growth and overall survival in allograft mice bearing Brca1-mutant tumors compared with AZD2281 or radiotherapy alone." (PMID 33767581, 2021). "PARP inhibition killed tumor cells by coordinating with the considerable accumulation of genomic defects by HR deficiency, rather than the mutated BRCA1/2." (PMID 34869593, 2021). "BRCA1 has a tumor suppressor function and it has been documented previously that knocking down the expression of BRCA1 in BRCA1 wild-type cells resulted in an increase in the rate of proliferation, increase in the propensity to grow in soft agar, to migrate and to invade matrigel." (PMID 34228231, 2021). "Sixteen of the occult tumours occurred in BRCA1 PV carriers and five in BRCA2 carriers." (PMID 33152107, 2021). "PCI-24781 significantly inhibited tumor growth and downregulated DNA repair machinery (BRCA1, CHK1, RAD51, and O6-methylguanine-DNA- methyltransferase (MGMT)), increasing DNA double-strand breaks and causing apoptosis in the GBM cell lines, including an MGMT expressing cell line in vitro." (PMID 34696786, 2021). "Although BRCA1 and BRCA2 mutant tumours are the best-known associations of HR deficiency and intrinsically sensitive to PARP inhibitors, there are a wide range of other non-BRCA DNA repair genes associated with HR deficiency, including but not limited to ARID1A, ATM, PALB2, CHEK2 and FANCA." (PMID 34572747, 2021). "By the protein–protein interaction between PAFR and FAK and FAK and the Signal Transducers and Activators of Transcription (STAT1), the receptor promoted tumor progression and contributed to early malignant transformation of BRCA1-mutant ovarian epithelial cells." (PMID 34571986, 2021). "As a crucial tumor suppressor, BRCA1 functions in DNA damage repair and maintains genome integrity." (PMID 33623049, 2021). "Surprisingly the BRCA1 (V1804D) was detected in both the normal and tumor samples." (PMID 34504655, 2021). "Increased PD‐L1 mRNA levels in the GR group correlated with BRCA2 mutation status (p = 0.013) but not with BRCA1 mutations and PD‐L1 protein expression in tumor immune cells was significantly higher in those patients with mutations in BRCA2 (p = 0.029)." (PMID 33811746, 2021). "Meanwhile, aggressive pathologic features in BRCA1 mutation-carriers, such as the higher proportion of grade III tumors (73.0%), resulted in the rapid tumor growth, which has been also suggested as one of the most important underlying factors contributing to the FNR at imaging test." (PMID 34336698, 2021). "The overall prevalence of BRCA1/2 PV in 570 HGSC tumor samples was 16%." (PMID 33030818, 2021). "In addition, in up to 8% of affected patients, somatic BRCA1 and BRCA2 mutations can be found in tumor specimens." (PMID 34202525, 2021). "To uncover the molecular changes during BRCA1-deficency induced tumorigenesis, we separated the single cells (only mammary epithelial and tumor cells) as per their mouse origin because the tumorigenesis process may be different among individuals." (PMID 34815798, 2021).
tumor (continued). "BRCA1 is a tumor suppressor that functions in DNA damage repair." (PMID 33478572, 2021). "In fact, the treatment with glibenclamide, an inflammasome inhibitor, delayed tumor recurrence, blocked lung metastasis of the Brca1 mutant tumors, reduced the percentage of macrophages in relapsed tumors, and the mRNA levels of M2 macrophage markers (CD163, CD206, and Mgl2) in recurrent tumors." (PMID 33840390, 2021). "Therefore, BRCA2 is a classic tumor suppressor gene, similar to related tumor suppressors such as BRCA1 and PALB2, which also function in the cellular response to DNA damage and in the maintenance of genetic/genomic stability." (PMID 34356050, 2021). "In nine (17.0%) out of these 53 patients without a pathogenic gBRCA1/2 mutation, somatic BRCA1/2 mutation was observed in tumor specimens." (PMID 34202525, 2021). "We hypothesize that methylation conversion is either an active mechanism of resistance as the tumor reactivated BRCA1 in a response of therapy‐induced DNA double‐strand breaks (e.g., platinum‐based therapy)." (PMID 34601813, 2021). "In BRCA1/PALB2 mutated tumors, carboplatin was the most active drug in reducing tumor volume." (PMID 33782404, 2021). "Tumour BRCA1/2 (tBRCA1/2) tissue analysis can detect both sBRCA and gBRCA pathogenic mutations." (PMID 33808557, 2021). "Five mutations in PIK3CA, one in BRCA1 and one in IDH1 found in this study are FDA-recognized biomarkers (level 1) and one ERBB2 mutation is a standard care biomarker (level 2A), predictive of response to FDA-approved drugs in specific tumor types." (PMID 33500480, 2021). "This may be more pronounced in those undergoing neoadjuvant chemotherapy, which may delay the primary surgical decision, and may be particularly relevant in BRCA1, carriers whose tumours nearly always require chemotherapy." (PMID 33531640, 2021). "In addition, ART558 elicits DNA damage and synthetic lethality in BRCA1- or BRCA2-mutant tumour cells and enhances the effects of a PARP inhibitor." (PMID 34140467, 2021). "Thus, simulating the clinical situation using a mouse model, such as the Brca1-mutant tumor-bearing mouse model, is a useful strategy for testing treatment efficacy." (PMID 33767581, 2021). "Inhibition of KLF4 could efficiently block both DNA damage response and HR in BRCA1‐proficient, TNBC tumors that, in turn, generates synthetic lethality for BRCA1‐proficient TNBC tumor cells in combination with blocking PARP function." (PMID 33231937, 2020). "Using HGSOC cell lines from platinum-taxane refractory patients that do not harbor BRCA1/2 mutations, we tested the anti-tumor activity of CP, or PT alone or in combination with the AAK inhibitor alisertib (AL)." (PMID 32974133, 2020). "However, the well-known function of BRCA1, acting as a tumor suppressor, is related to the role of BRCA1 in promoting genomic stability." (PMID 33013205, 2020). "This study proposes that translational control may represent a novel molecular mechanism with potential clinical impact through which BRCA1 is a tumor suppressor." (PMID 32290274, 2020). "Hence, together with BRCA1, BRCA2 acts as a tumor suppressor; mutations in these genes will impede the cell’s ability to repair DNA damage, especially DNA DSBs." (PMID 32005245, 2020). "In this study, we identified that BRCA1, a tumour suppressor gene responsible for DNA double‐strand break‐repair, is the cellular target of BART2‐5p, BART12, BART17‐5p and BART19‐3p, in which BART17‐5p and BART19‐3p constitute ~8.6% of the total viral miRNAs in NPC." (PMID 33074587, 2020).
tumor (continued). "Its overexpression correlates also with the histologic grade of sporadic and invasive ductal BC when also BRCA1 tumor suppressor function is abolished by the downregulation of the protein levels, underlying that both contribute to the pathogenesis of this type of tumor." (PMID 32517194, 2020). "Furthermore, the correlation between BRCA1 hypermethylation and the main pathological features of tumor was analyzed." (PMID 32856871, 2020). "Although it has been demonstrated that BRCA1 played a prominent role in cell metabolic reprogramming, there was no sufficient evidence to support the function and mechanism by which BRCA1 regulated glycolysis in tumor metabolism by means of transcriptional molecule." (PMID 32470015, 2020). "Although clinical trials have shown poly (ADP-ribose) polymerase inhibitors (PARPi) response rates of around 40% in women who carry a mutation in the BRCA1/2 genes, PARPi is responsible for tumor suppression, but not for complete tumor regression." (PMID 32316968, 2020). "In a multivariate prediction model, we show that stathmin protein assessed by IHC is independently associated with BRCA1 status among ER negative tumours." (PMID 32076022, 2020). "The inappropriate DSB repair caused by defective BRCA1/2 often leads to chromosomal dislocation, although this is not sufficient to drive tumor formation per se." (PMID 32980867, 2020). "Endogenous, glucose-derived lactate may increase transcription of oncogenes and tumour suppressors such as BRCA1 and may be preferred over glucose by tumour cells for oxidative metabolism." (PMID 33212987, 2020). "Furthermore, BRCA1/BRCA2 tumor sequencing allows the detection of both germline and somatic variants in a single test, the latter having a frequency ranging from 4% to 7%." (PMID 33008098, 2020). "Here, we report translational regulation as a novel pivotal function of BRCA1 that may represent a novel mechanism through which BRCA1 exerts its tumor suppressive activity." (PMID 32290274, 2020). "Here, we asked whether translational control could be a novel function of BRCA1 that contributes to its tumor suppressive activity." (PMID 32290274, 2020). "Of the 57 hypermethylated cases, 51 (89.5%) showed concurrent LOH of BRCA1 (tumor cell content by WGS range 23–82%) with the six remaining cases having low estimated tumor cell content (between 11% and 23% by WGS), which possibly interfered with the copy number analysis." (PMID 32719340, 2020). "In addition, BRCA2-related tumours are mainly oestrogen receptor (ER)-positive, and BRCA1-related tumours are mainly ER-negative." (PMID 31948486, 2020). "Both molecules have shown an exquisite anti-tumoral activity towards BRCA1/2 deficient tumours with no adverse effects." (PMID 32098397, 2020). "Additionally, BRCA1 (3326A>T) and BRCA2 (1342A>C) mutations were also detected in tumor tissues of II3." (PMID 32356124, 2020). "The pro-tumorigenic role of BRCA1 “tumor suppressor” in RB is intriguing." (PMID 32572160, 2020). "The commonly up-regulated gene in all TME cells, BRCA1, encodes a nuclear phosphoprotein involved in maintaining genomic stability, DNA repair of double-stranded breaks, tumor suppression and in alternative non-homologous end-joining at uncapped telomeres." (PMID 32842712, 2020).
tumor (continued). "As suggested by the authors, BRCA1 methylation detected in the primary tumor may have been lost following this first treatment, thereby explaining the lack of response to carboplatin in the advanced tumors." (PMID 32175521, 2020). "At the same time, a compensatory mechanism for the expression of CDK12-dependent HR genes (particularly BRCA1/2) in the tumour background must exist, and might even be essential for tumour onset and/or survival." (PMID 34316683, 2020). "Interaction between these genes affects double-strand break repair and apoptosis suggesting that this protein may play an important role in BRCA1 tumour suppression." (PMID 33086730, 2020). "For instance, in HR-deficient tumour cells, in the absence of BRCA1/BRCA2, PARP1 inhibition has been shown to have cytotoxic side-effects." (PMID 31940791, 2020). "However, there are a few examples of interest for performing immunohistochemistry to evaluate BRCA1 protein and nuclear expression for BRCA2-associated tumor." (PMID 32481735, 2020). "Because of this phenomenon, HBOC patients with germline BRCA1 and BRCA2 mutations have an increased risk for the development of a number of neoplasms, particularly those arising in the breast as well as ovary and fallopian tube (hereby referred to as “tubo-ovarian cancer”)." (PMID 33117676, 2020). "In addition, only 9 and 3 genes were differentially expressed between sporadic tumours and BRCA1- and BRCA2-associated tumours, respectively." (PMID 33081408, 2020). "Despite the BRCA1 mRNA level in NPC tumours (n = 55) being significantly higher than in non‐cancerous NP tissues (n = 21; P = 0.0189) in the qRT‐PCR analysis, reduction of BRCA1 protein expression in NPCs was found in an independent cohort of 30 normal NPs and 41 NPCs (P = 0.0005)." (PMID 33074587, 2020). "Specifically, 36 cases out of the HRD tumor population exhibited low levels of BRCA1 mRNA." (PMID 32719318, 2020). "RANKL inhibition also significantly suppressed the proliferation of tumor organoids derived from BRCA1 mutant human breast biopsy specimens, and RANKL/RANK pathway blockade strongly reduced tumorigenesis in patient-derived xenograft (PDX) breast tumor mouse model." (PMID 32850393, 2020). "Several clinical, genomic, and immune factors have been correlated with long-term survival, including age, stage, tumor grade, optimal or sub-optimal primary cytoreductive surgery, homologous-recombination deficiency (HRD), BRCA1/BRCA2 mutations, and the presence of intra-tumoral immune cells." (PMID 32156016, 2020). "Moreover, the BRCA1 loss mutation, like oncogene activation (RAS, NF-κB, TGF-β), in cancer cells will drive the initiation of metabolic symbiosis phenotype between tumor cells and fibroblasts in both primary and metastatic cancers." (PMID 33489906, 2020). "Given the simultaneous inhibition of BRCA1 and RAD51, the combination of BET inhibitors with PARP inhibitors may further increase the sensitivity of HR deficient, BRCA mutated tumor cells by further downregulating expression of RAD51." (PMID 32180937, 2020). "In exact, BRCA1-null tumor cells corresponded to mesenchymal, basal and AvP lineages." (PMID 32840210, 2020). "Tumors derived from orthotopically injected CST-mCherry cells in FVB-GFP mice showed sensitivity to cisplatin, providing a new model to study the cooperation of BRCA1-KO, mCherry-positive tumor cells and the GFP-expressing stromal compartment in therapy resistance and metastasis formation." (PMID 32053991, 2020). "This may occur either through active promoter demethylation or through positive selection of pre-existing tumor cells with low levels of BRCA1/2 promoter methylation after PARP inhibitor treatment." (PMID 32180937, 2020). "BRCA1 is a tumour suppressor gene, involved in double strand DNA break repairs." (PMID 32419845, 2020).